HSF1 (heat shock transcription factor 1)
Diseases named in the same sentence as HSF1 in open-access papers (continued):
Sharing a sentence is not in itself a finding about the gene and the disease.
breast cancer (continued). "The constitutive activation of HSF1 in breast cancer contributes to the expression of a group of malignant program genes in addition to the heat shock proteins and this HSF1-regulated malignant program was also active in colon and lung cancer." (PMID 25199534, 2014). "An influence of HSF1 on mTOR signaling is not clear, since different results were obtained in Hsf1-/- MEFs and in human breast cancer cells after HSF1 silencing." (PMID 24467529, 2014). "Although hemizygous deletion of HSP90 isoforms and HSF1 were found in 4.37% to 18.09% of breast cancer samples, homozygous deletion was uncommon." (PMID 22510516, 2012). "Only 1 of 481 (2%) breast cancer samples had two allele deletions on the TRAP1 coding region, and no patients carried a homozygous deletion of other HSP90 isoforms and HSF1, suggesting that loss of expression of HSP90 is a rare event in breast cancer." (PMID 22510516, 2012). "Increased expression of each of the heat shock protein (HSP) 90 isoforms, as well as HSP transcriptional factor 1 (HSF1), was correlated with poor prognosis in different subtypes of breast cancer." (PMID 22510516, 2012). "For instance, in HER-2 (human epidermal growth factor receptor-2 oncogene) expressing cells, in aggressive breast cancer models, HSF1 knockdown is accompanied by a specific down-regulation of HSP27 and HSP70 expression." (PMID 24212658, 2011). "As the central regulator of HSP expression, HSF1 is also a target in designing anti-breast cancer therapies." (PMID 21978374, 2011). "In the present study, human breast cancer cell line Bcap37 was stably transfected with constitutively active HSF1 (cHSF1) or HSF1 specific siRNA (HSF1i) to establish increased or decreased HSF1 expression levels." (PMID 20459615, 2010). "HSF1’s prooncogenic role has also been described in mouse mammary tumors." (PMID 40287736, 2025). "Additionally, HSF1 seems to prevent CD8 + T-cell recruitment to breast cancer microenvironment by downregulating the expression of CCL5." (PMID 40287736, 2025). "Thus, the present study aimed to determine the interactions between Bag‐1 and HSPs (HSP90, HSP70 and HSP27) that contribute to HSF1 phosphorylation in breast cancer cells." (PMID 39049197, 2024). "As the central moderator of the HSP discourse, HSF1 may be a platform for innovative ways to treat breast cancer." (PMID 38956273, 2024). "Thus, the heat shock-independent activation of HSF1 augments the breast cancer stem cell phenotype and confers drug resistance." (PMID 39682216, 2024). "In addition, the basal levels of anti-apoptotic stress proteins such as Hsp27 and Hsp70, both regulated by HSF1, are lower in colorectal cancers than in lung and breast cancer cells." (PMID 38229111, 2024). "Recently, a HER2-Akt-HSF1 Slug axis was described in EMT regulation in breast cancer cells." (PMID 38291468, 2024). "Moreover, elevated HSF1 levels correlate with invasive features of breast cancer cells, and the use of the HSF1 inhibitor DTHIB significantly inhibits their growth." (PMID 37894333, 2023). "Furthermore, microRNA-615-5p enhanced apoptosis and reduced the development of breast cancer by downregulating HSF1 expression." (PMID 37958341, 2023). "Currently, clinical trials of the HSF1 inhibitors quercetin and triptolide are being conducted for squamous cell carcinoma, gastric cancer, and breast cancer, although it remains unknown whether these drugs are specific inhibitors of HSF1." (PMID 37762105, 2023). "HSF1 is involved in multiple pathways related to breast cancer, indicating that it could be a potential target for targeted breast cancer treatment." (PMID 37958341, 2023).
breast cancer (continued). "To test this hypothesis, we examined the expression of the genes residing in between the GSDMD and HSF1 in multiple breast cancer genomic datasets in the case of breast cancer (METABRIC) and breast invasive carcinoma (TCGA, Firehose Legacy)." (PMID 36497066, 2022). "In addition, the Akt has been reported to phosphorylate and activate HSF1 independently of heat-shock, leading to epithelial-mesenchymal transition in breast cancer cells." (PMID 35370703, 2022). "In HER2-positive breast cancer, HSF1 promotes malignant transformation and metastasis." (PMID 35311075, 2022). "Interestingly, research by Yallowtiz and colleagues showed that lapatinib-resistant breast cancer cells have chronically activated HSF1 and heat shock proteins, but that these cells can be sensitised to treatment using HSF1 inhibitors." (PMID 35326716, 2022). "Nevertheless, the phosphorylation at another amino acid residue, Thr120, by PIM2 protects it from being degrading by FBXW7 and results in the accumulation of HSF1, which subsequently induces the expression of PD-L1 in breast cancer and enhances growth of breast cancer." (PMID 35814468, 2022). "Given that HSF1 plays a role in cancer progression, metastasis, and drug resistance, and our previous finding that EGR4 is regulated by HSF1 in breast cancer cells, the aim of this study was to more fully investigate the potential oncogene EGR4 and its regulation by HSF1." (PMID 35326716, 2022). "Therefore, the MCF7/LCC9 models recapitulate clinical observations made for HSF1 and ERα in breast cancer." (PMID 33593922, 2021). "In addition, HSF1 was overexpressed in a model of endocrine-resistant breast cancer cells, which correlated with a decrease in ERα-activated genes." (PMID 33593922, 2021). "We found that estrogen action may be supported by HSF1, a deficiency of which in ER-positive MCF7 breast cancer cells slows down the mitogenic effect of estrogen." (PMID 34783649, 2021). "These analyses suggest that the action of HSF1 and its effect on metastasis formation may differ in ER+ versus ER− breast cancers." (PMID 34783649, 2021). "Notably, higher levels of phosphorylation of S303 and 307 of HSF1 were clearly observed in breast cancer, ovarian cancer, colon cancer, and LUAD in the present study." (PMID 34239690, 2021). "Therefore, evidence suggests that HSF1 is an important transcription factor in the progression toward aggressive forms of breast cancer including endocrine resistance." (PMID 33593922, 2021). "Previous studies have suggested that high levels of HSF1 may worsen the outcomes for patients with estrogen receptor-positive breast cancers, but it remains unclear how HSF1 acts in breast cancer cells." (PMID 34783649, 2021). "Furthermore, we analyzed global gene expression profiles in breast cancers with different ERα and HSF1 statuses." (PMID 34783649, 2021). "Experimental data indicate that the level of HSF1 can be used to predict response to treatment, while HSF1 targeting may improve the efficacy of breast cancer treatment and prevent the development of metastases." (PMID 34783649, 2021). "Relationship between ERα and HSF1 expression in breast cancer." (PMID 34783649, 2021). "Therefore, out of all breast cancer cases, we selected four groups (numbered from I to IV) characterized by significantly different levels of ERα (mRNA and protein level) and HSF1 (mRNA) expression: ER−/HSF1low, ER−/HSF1high, ER+/HSF1low, and ER+/HSF1high." (PMID 34783649, 2021). "Many genetic association studies have documented the potential impact of HSF1 and HSF2 on human health and diseases and tried to connect HSF1 gene variantsand its altered levels, to schizophrenia, bipolar disorder, attention deficit hyperactivity disorder and breast cancer." (PMID 35540693, 2021). "Investigation of these protein interactions may reveal a role for HSF1 in genome integrity in HD as previously shown for mammary tumors." (PMID 33208463, 2021).
breast cancer (continued). "Therefore, to further study the significance of the interaction between ERα and HSF1 in actual breast cancer, we utilized RNA-seq data deposited in TCGA database." (PMID 34783649, 2021). "In this connection, naphthazarin and its derivative S64 were shown to radiosensitize breast cancer MCF-7 cells or inhibit the DNA-binding activity of HSF1 and deplete GSH in hypoxic colon cancer cells; these findings suggest a potential use of both agents for targeting hypoxic tumors." (PMID 33806538, 2021). "Besides, this study also pointed out that the HSF1-regulated transcriptional targets were hyperactivated in a wide range of human malignancies and possessed potential prognostic value, especially in breast cancer and colon cancer." (PMID 32110802, 2020). "Given that other markers of HSF1 activity, such as CaSig or nuclear localization, are related to breast cancer outcomes, these findings suggest that the prognostic value of HSF1 mRNA levels may be specific to different cancer types." (PMID 32331382, 2020). "Hence, it is possible that a positive feedback loop engages ERα and HSF1 in ERα-positive breast cancers." (PMID 32408596, 2020). "Importantly, the HSF1-CaSig provides a predicting marker for cancer severity, since it was shown to correlate with poor patient survival in breast cancer patients." (PMID 32408596, 2020). "In addition, HSF1 was involved in the stem cell phenotype in human breast carcinoma cells, such as MDA-MB-231 and MCF7, which were rich in HSF1 phosphorylated on the activating site, S326, and low in HSF1 phosphorylated on the repressive site, S303." (PMID 32331382, 2020). "This is a very important finding bearing in mind that up to 80% of all breast cancer cases rely on supplies of the estrogen to grow, while HSF1 is frequently overexpressed in breast cancer and its high level in ER-positive cases negatively correlates with the survival time of patients." (PMID 31614463, 2019). "Because FAM3C overexpression or silencing is associated with HSF1 mRNA level change in breast cancer cells, it is reasonable to speculate that FAM3C enhanced HSF1 gene transcription." (PMID 30887707, 2019). "In breast cancer, since the activation of AKT and the subsequent activation of HSF1 by p-AKT shortens the metastatic intervals of tumor cells, inhibition of the AKT/HSF1 signaling axis resulted in the reduced number of metastatic breast cancer cells and cancer stem cells." (PMID 31878360, 2019). "HSF1 inhibition also repressed YY1‐induced migration of breast cancer cells." (PMID 30887707, 2019). "Thus, HSF1 has been shown to contribute to malignant transformation and tumor cell survival in breast cancer and multiple myeloma (MM), supporting earlier findings in models of spontaneous malignancy." (PMID 31535086, 2019). "This study aimed to determine whether and how FAM3C activated HSF1 transcription to promote the proliferation and migration of breast cancer cells." (PMID 30887707, 2019). "Inhibition of HSF1 also blocked TGFβ‐induced migration of breast cancer cells." (PMID 30887707, 2019). "Not surprisingly, HSF1 protein levels are elevated in 80% of breast cancer cases that are associated with poor prognosis." (PMID 29799521, 2018). "Therefore, we assessed HSF1 as a general sensor of proteotoxic stress and correlated its activity with sensitivity to three separate small molecule Hsp90 inhibitors in seven breast cancer cell lines representing each of the different cancer subtypes." (PMID 30138434, 2018). "To investigate the potential of HSF1 as a predictive marker for Hsp90 inhibition, we selected seven breast cancer cell lines representing Luminal A (MCF-7, T-47D), Luminal B (BT-474), basal (BT-549, BT-20, MDA-MB-468) and HER2 positive (BT-474, SK-BR-3) subtypes." (PMID 30138434, 2018).
breast cancer (continued). "We therefore selected the most resistant breast cancer cell lines (SK-BR-3, T-47D), that also show the highest increase in Ser326 phosphorylation of HSF1 upon Hsp90 inhibition, and cultivated them in elevated temperature (39 °C) to increase the demands on chaperone system." (PMID 30138434, 2018). "Thus, the kinome adaptation in lapatinib-resistant ERBB2-positive breast cancer cells is governed, at least in part, by HSF1-mediated heat shock pathway, providing a novel potential intervention strategy to combat resistance." (PMID 29799521, 2018). "In breast cancer, HSF1 specifically induces a cancer stem cell phenotype in vitro." (PMID 29757368, 2018). "Hence, HSF1 protein levels are elevated in 80% of breast cancer, leading to enhanced expression of its targets, including Hsp90." (PMID 27791982, 2017). "Indeed, HSF1 can be activated directly in mammary cancer through the Her2 pathway by activated Akt which mediates GSK3 inhibition." (PMID 28484363, 2017). "In addition to breast cancer, elevated levels of nuclear HSF1 is observed in melanoma, lung, pancreatic, prostate, colon and cervical cancers." (PMID 28914774, 2017). "Since combined inhibition of AKT and HSF1 resulted in a synergistic effect in killing breast cancer cells in vitro, we asked whether this treatment strategy can be translated into an in vivo effect." (PMID 29088759, 2017). "Unfortunately, it is unknown if AKT and HSF1 are co-activated in breast cancer subtypes outside of the HER2-enriched subtype." (PMID 29088759, 2017). "Furthermore, high tumor levels of HSF1 were correlated with poor clinical outcomes in several of these cancer types, including breast cancer." (PMID 29088759, 2017). "HSF1 has been shown to be involved in HER2-positive breast cancer." (PMID 29088759, 2017). "However, it is recognized that the TCGA dataset has limited followup/survival information, so we further analyzed the prognostic relevance of HSF1 in breast cancer in a publically available large (n = 1881) Affymetrix-based gene expression dataset." (PMID 27713164, 2016). "In addition, hyperphosphorylation of serine 326, which is upregulated in breast cancer compared with its normal counterparts, has been used as a biomarker to indicate HSF1 activation in immortalized primary mammary epithelial tumor cells." (PMID 27487129, 2016). "In order to confirm that differences observed could be attributed to technical and tissue sampling issues and not related to biological relevance, we further evaluated the role of HSF1 in breast cancer using publically available datasets." (PMID 27713164, 2016). "These analyses confirm that amplification is the most common alteration, while mutations of HSF1 are not frequent in breast cancer." (PMID 27713164, 2016). "Moreover, pharmacological inhibition of Her2 strongly suppresses HSF1 activation in vitro and in the Her2 mouse transgenic model, which correlates with reduced mammary tumor progression." (PMID 25954247, 2015). "Overexpression of HSF1 was observed in a broad range of cancer cell lines and human tumors including colorectal cancer, breast cancer, lung cancer, hepatocellular carcinoma, endometrial carcinoma, oral squamous cell carcinoma, glioma, melanoma and multiple myeloma." (PMID 26511079, 2015). "Moreover, recent studies demonstrate existence of a linear signaling pathway between Her2 and HSF1 in Her2-positive breast cancer, both in vitro and in vivo." (PMID 25954247, 2015). "Also sulphoraphane and phenethyl isothiocyanate, a naturally occurring isothiocyanates have been shown to induce apoptosis in breast cancer cells by targeting HSF1 and HSPs." (PMID 24467529, 2014). "HSF1 has recently been shown as a facilitator of transformation in breast cancer." (PMID 25969759, 2012).
breast cancer (continued). "Supporting our finding in the heart, HSF1 protein levels and activation were shown to be induced by ErbB2 over-expression in a breast cancer cell line, while the mechanism of this ErbB2 connection to HSF1 is still unknown." (PMID 22912742, 2012). "Furthermore, amplification of HSP90AA1 and/or high-level amplification of HSF1 collectively represents a group of breast cancer samples with up-regulated HSP90AA1 mRNA expression (P = 9.62 × 10-8, n = 481, Mann-Whitney U Test)." (PMID 22510516, 2012). "It is speculated that differential regulations of HSF1 mRNA by variant and ancestral miR-608 result in the differential HSF1 levels, leading to differential development of HER2+ breast cancer." (PMID 22586447, 2012). "Moreover, this HSF1 cancer program was found to be very significantly and broadly associated with poor outcomes such as metastasis and death in breast cancer, whereby patient survival decreases dose dependently as HSF1 nuclear levels increase." (PMID 24278719, 2012). "In addition, HSF1-mediated control of breast cancer cell senescence was due, at least partly, to the regulation of HSP70 and HSP27 expression." (PMID 24212658, 2011). "Down-regulation of HSF1 leads to decreased survivin expression in breast cancer cells." (PMID 21978374, 2011). "Indeed, the formation of a complex between beta-catenin, HSP27 and HSF1 has been detected in breast cancer biopsies." (PMID 24212658, 2011). "Collectively, the results of the present study highlighted that Bag‐1 overexpression in HER2+ breast cancer cells, specifically BT‐474 cells, may regulate the expression of HSPs through promoting HSF1 phosphorylation at Ser326, through the PI3K/AKT/mTOR pathway." (PMID 39049197, 2024). "However, HSF1 functions in breast cancer, and Hsp27 levels may increase a second time during this change." (PMID 38956273, 2024). "Moreover, p53LOH breast cancers (BRCA TCGA) also exhibited upregulated HSF1 targets." (PMID 34188043, 2021). "Therefore, this study was undertaken to examine whether targeting HSPAs- or HSF1-mediated cytoprotection would increase the effectiveness of MA in lung and breast cancer cells." (PMID 34200371, 2021). "The first indication that HSF1 might be constitutively active in human tumors was that its gene targets, HSPs, such as Hsp27 and Hsp70, almost exclusively silent in normal tissues, were avidly expressed in breast cancer and other malignancies." (PMID 32331382, 2020). "Accumulating evidence shows that HSF1 exerted strikingly multifaceted effects on the carcinogenesis process of a variety of hematologic and solid tumor malignancies (e.g., T-cell acute lymphoblastic leukemia, chronic lymphocytic leukemia, breast cancer, gastric cancer, CRC, and so on)." (PMID 32110802, 2020). "Thus, HSF1-mediated DDR is a major mechanism of the addiction of BRCA1-null mammary tumors to HSF1, and could be a target for the treatment of a specific type of malignant tumors." (PMID 29158484, 2017). "Additionally, this may indicate that inhibition of HSF1 may sensitize breast cancer cells to inhibition of AKT, thereby enhancing the efficacy of AKT inhibition." (PMID 29088759, 2017). "A collection of HSP90AA1, HSP90AB1 and HSF1 amplifications defined a subpopulation of breast cancer with up-regulated HSP90 gene expression, and up-regulated HSP90 expression independently elevated the risk of recurrence of TNBC and poor prognosis of HER2-/ER+ breast cancer." (PMID 22510516, 2012). "HSF1 may partly participate in breast cancer progression by inducing specific HSPs, mainly HSP27." (PMID 24212658, 2011). "Notably, HSF1 plays an additional role in the etiology of breast cancer." (PMID 24212658, 2011).